TUBB3 (tubulin beta 3 class III)
Diseases named in the same sentence as TUBB3 in open-access papers (continued):
Sharing a sentence is not in itself a finding about the gene and the disease.
breast carcinoma (continued). "In addition, patients in this study were not treated with estrogen and therefore further studies are required to assess the clinical value of ER in TUBB3 regulation in breast cancer." (PMID 35573698, 2022). "Finally, Kaplan–Meyer survival curve analysis validated the decrease in overall survival for patients with breast cancers having the highest levels of innervation as reflected by the expression of the neuronal marker TUBB3." (PMID 34810279, 2022). "Other DEGs that were upregulated in the PTX-res cells included the β-tubulin encoding gene TUBB3, which has been associated with paclitaxel resistance and FZD2, a member of the Wnt receptor Frizzled family, which has been shown to endow breast cancer cells with drug resistance." (PMID 36078127, 2022). "TUBB3 is related to breast cancer metastasis to the brain and metastasis in pancreatic cancer." (PMID 28678795, 2017). "Comparing our findings to other tumors in the same review, the degree of high TUBB3 expression in our group was higher than that which has been observed in breast cancer (43% of 196 cases) and cancer of unknown primary site (55% of 40 cases)." (PMID 24396456, 2014). "Interestingly, another brain-specific tubulin isoform, TUBB3 has been shown to promote breast cancer brain metastatic potential without affecting the growth of the primary tumor, likely by enhancing the invasive properties of breast cancer cells." (PMID 39962586, 2025). "Recently, expression of tubulin genes, TUBB3 and TUBB6, was significantly downregulated in the taxane-resistant breast cancers." (PMID 35677170, 2022). "The result showed that the protein expression of TUBB3, MCM2, FN1, S100A7, and TFF1 was increased, and the protein expression of MYOC was downregulated in luminal A breast cancer, which was consistent with the result of RNA expression." (PMID 35692369, 2022). "TUBB3, an established SOX11 target, regulates cell growth and invasive potential of ER- breast cancer cells." (PMID 32909943, 2020). "The protein expression results of TUBB3, MCM2, MYOC, FN1, S100A7, and TFF1 were consistent with the mRNA expression result COL10A1, LEP, PLIN1, PGM5-AS1, and TRHDE-AD1 were capable of discriminating luminal A breast cancer and normal controls." (PMID 35692369, 2022). "Thus, many studies have shown that the expression and/or co-expression of several genes, such as ERCC1, RRM1, TOP1, TOP2α, TUBB3, TYMS, and GSTP1, in tumor tissues is closely related to chemoresistance and prognosis in breast cancer patients (BC)." (PMID 35204496, 2022). "Besides, the interaction of exogenous RILPL2 with TUBB3 resulted in the downregulation of breast cancer cell proliferation and migration and upregulation of PTEN expression by promoting destabilization of TUBB3." (PMID 34095226, 2021). "In the same study, oestradiol-induced TUBB3 expression could not be reproduced in estrogen receptor (ER) negative breast cancer cell lines, and was abrogated after exposure to the ER antagonists tamoxifen and fulvestrant in several ER-expressing breast cancer cell lines." (PMID 35573698, 2022). "More recent studies in NSCLC and breast cancer cells have revealed a very interesting dose-dependent divergence in response to DTX, based on the presence or absence of TUBB3." (PMID 35631517, 2022).
tubulinopathies (18 papers, 2014 to 2025). "This condition is predominantly associated with TUBB2B mutations and to a small set of TUBB3 substitution, among tubulinopathies." (PMID 36769099, 2023). "Clearly the cells can compensate in the absence of Tubb3 with other β-isotypes, indicating that these TUBB3-associated tubulinopathies are acting in a different mechanism that cannot be solely explained by changes in isotype expression due to haploinsufficiency." (PMID 36406756, 2022). "Mutations in seven genes encoding α- (TUBA1A), β- (TUBB2A, TUBB2B, TUBB3, TUBB4A, TUBB5), and γ- (TUBG1) microtubulin are linked to extensive overlapping brain malformations or tubulinopathies." (PMID 40948494, 2025). "As neuroradiological findings were suggestive of TUBB3 tubulinopathy, the patient was referred for genetic evaluation." (PMID 39336781, 2024). "In fact, primary neurodegenerative tubulinopathies, caused mainly by mutations in genes encoding the components of the tubulin cytoskeleton, especially in TUBA4A, TUBB2A, and TUBB3 genes, have been excellently reviewed and comprehensively discussed recently." (PMID 36352320, 2023). "These can be either primary neurodegenerative tubulinopathies (caused by mutations in genes coding for components of microtubules, like TUBA4A, TUBB2A, and TUBB3) or disorders caused by various pathogenic interactions and transactions between different compounds and tubulin cytoskeleton." (PMID 36352320, 2023). "The present case resembles TUBA1A-associated tubulinopathy, rather than classic TUBB3 CFEOM3, where nystagmus was present in 3/29 (10.3%) cases, and no CFEOM phenotypes were observed." (PMID 33921132, 2021). "Although optic nerve hypoplasia has been reported in tubulinopathies, there were no reports of infantile nystagmus in patients with optic nerve hypoplasia who had TUBB3 mutations." (PMID 33921132, 2021). "Fundamentally, the mutant tubulin protein produced by heterozygous tubulinopathy mutations represents no more than half of the tubulin pool in the cell; and in some cases, such as TUBB3 tubulinopathies, may represent a much smaller fraction." (PMID 34869359, 2021). "Although renal anomalies have been reported in subjects with Kallmann syndrome, TUBB3 is not expressed in the kidneys, and there have not been reports of renal disease associated with tubulinopathies." (PMID 34652576, 2021). "Similarly, it is reasonable to consider that tubulinopathy mutations, such as TUBA1A-V409I/A and TUBB3-D417H/-R262H may have allosteric effects across the heterodimer that impact tubulin conformations and interactions with MAPs." (PMID 36406756, 2022). "Other “tubulinopathies” genes include TUBA1A, TUBB2A, TUBB2B, TUBA8, TUBB3, TUBB, and TUBG1, which were found to be DEGAs in various brain regions." (PMID 34638726, 2021). "We identified a TUBB6 p.(Glu410Lys) variant in syndromic familial ptosis pedigree ENG_CML; this substitution has been reported as P/LP for tubulinopathies in four paralogs (TUBB2A, TUBB2B, TUBB3, and TUBB4A; ClinVar Variation IDs: 986830, 1195195, 6967, 135658)." (PMID 38585811, 2024). "In recent years, an increasing number of tubulin genes were linked to a clinically heterogeneous group of disorders, the “tubulinopathies” (TUBA1A, MIM#602529; TUBA8, MIM#605742; TUBB2A, MIM#615101; TUBB2B, MIM#612850; TUBB3, MIM#602661; TUBB, MIM#191130; TUBG1, MIM#191135)." (PMID 30744660, 2019).
gastric cancer (16 papers, 2011 to 2025). A primary or metastatic malignant neoplasm involving the stomach. "Yiqi Jianpi Huaji Decoction can inhibit gastric cancer cell proliferation, induce apoptosis, and increase sensitivity to chemotherapeutic agents by decreasing the expression of TUBB3, MRP, P-gp, and STMN1." (PMID 36210831, 2022). "As expected, TUBB3 is shown to be higher expressed in various cancers than that in healthy control, including gastric cancer (31.6 ± 17.8 ng/mL vs. 16.9 ± 3.8 ng/mL, p < 0.001)." (PMID 28056823, 2017). "Other studies using more permissive guidelines for high expression than those in our study have also revealed lower rates of high TUBB3 expression in head and neck cancer (40% of 80 cases) and gastric cancer (30% of 20 cases)." (PMID 24396456, 2014). "In conclusion, in advanced gastric cancer, TUBB3 was a predictive marker for taxane-cisplatin chemotherapy." (PMID 24053422, 2013). "A small cohort study of advanced gastric cancer patients who were receiving preoperative docetaxel-based chemotherapy showed a correlation between TUBB3 expression and a poor response to chemotherapy." (PMID 24053422, 2013). "A plethora of studies has consistently emphasized the notable correlation between elevated TUBB3 expression and unfavorable prognoses across various malignancies, including lung, ovarian, and gastric cancers, establishing it as a prognostic indicator for cancer recurrence." (PMID 38562930, 2024). "Furthermore, lower expression of TUBB3 was observed in female patients (P = 0.026) and patients having a family history of gastric cancer (P = 0.025)." (PMID 28056823, 2017). "The UGT1A1 polymorphism may be useful to screen the risk population of gastric cancer, while TYMS, TUBB3 and STMN1 may be potential biomarkers for prognosis and chemotherapy guidance." (PMID 28056823, 2017). "This study was designed to demonstrate the clinical implications of TP and TUBB3 expressions in capecitabine plus paclitaxel chemotherapy for advanced gastric cancer patients, and to identify potential predictors for patients with gastric cancer treated with capecitabine plus paclitaxel." (PMID 21586171, 2011). "Our findings suggest UGT1A1 polymorphisms may be useful to screen the risk population of gastric cancer and schedule the appropriate pretreatment to improve the overall survival, while TYMS, TUBB3 and STMN1 may be potential biomarkers for prognosis and chemotherapy guidance." (PMID 28056823, 2017). "We analyzed the significance of TUBB3 expression, along with that of excision repair cross-complementation group 1 (ERCC1) in recurrent and metastatic gastric cancer patients receiving taxane-based first-line palliative chemotherapy." (PMID 24053422, 2013). "Additional prospective, randomized controlled trials are needed to identify the true significance of TUBB3 and ERCC1 in the prognosis of gastric cancer." (PMID 24053422, 2013). "High Tubulin beta-3 chain (TUBB3) expression is related to a poor chemotherapy response and adverse prognosis in gastric carcinoma, pancreatic ductal adenocarcinoma and non-small cell lung carcinoma." (PMID 23665903, 2013). "The results of immunohistochemistry showed that the protein expression levels of RBP7, DES, SPP1, VIP, and PRKCG in gastric cancer tissues were higher than those in normal tissues, while PNOC, TNFRSF12A, and TUBB3 proteins are less expressed in gastric cancer tissues than normal tissues." (PMID 35174205, 2022). "Class III β-tubulin (TUBB3) is a prognostic marker in various tumors, but the role of TUBB3 in advanced gastric cancer is not clearly defined." (PMID 24053422, 2013). "The expressions of TYMS, TUBB3 and STMN1 were significantly associated with the clinicopathological characteristics of age, gender and family history of gastric cancer, but not with differentiation, growth patterns, metastasis and TNM staging in patients with gastric cancer." (PMID 28056823, 2017).
gastric cancer (continued). "Our findings suggested that, in Chinese advanced gastric cancer, TP positive & TUBB3 negative expressions might predict response and prognosis to capecitabine plus paclitaxel chemotherapy." (PMID 21586171, 2011). "Therefore, the present study was to investigate whether the genes ERCC1, BRCA1, TYMS, RRM1, TUBB3, STMN1 and TOP2A are underlying biomarkers for patients with gastric cancer, which, to our knowledge, has not been performed." (PMID 28056823, 2017).
non-small cell lung carcinoma (16 papers, 2010 to 2024). A group of at least three distinct histological types of lung cancer, including non-small cell squamous cell carcinoma, adenocarcinoma, and large cell carcinoma. "The role of TUBB3 has been studied in non-small cell lung cancer (NSCLC), and it has been shown to be associated with resistance to anti-tubulin agents, including taxanes." (PMID 24053422, 2013). "On the other hand, class III β-tubulin (TUBB3) is a predictive marker of vinorelbine sensitivity in non-small cell lung cancer." (PMID 35721082, 2022). "In contrast to Semaphorin-6A and ZEB1, the overexpression of the Snail family zinc finger transcription factor SLUG in non-small cell lung cancer cells suppressed expression of TUBB3/βIII-tubulin, as well as the β-tubulin isotype, TUBB4A/βIVa-tubulin." (PMID 35573698, 2022). "In this study, we aimed to investigate the predictive effect of BRCA1, STMN1, MAPT and TUBB3 on the prognosis of patients with non-small cell lung cancer (NSCLC)." (PMID 29113350, 2017). "A number of studies have examined the relationship between the expression of the class III β-tubulin (TUBB3) and the treatment responses to the taxane/vinorebine-based chemotherapy in patients with non-small cell lung cancer (NSCLC)." (PMID 24705847, 2014). "Surprisingly, we observed an increase in TUBB3 protein levels in taxol-resistant RPE cells compared to control DMSO-treated cells, similar to what was observed previously in the A549-T24 non-small-cell lung cancer and DU-145 prostate carcinoma cells." (PMID 29069726, 2017).
colorectal cancer (15 papers, 2017 to 2024). A primary or metastatic malignant neoplasm that affects the colon or rectum. "In colorectal cancer, elevated TUBB3 expression is associated with invasive phenotypes in both genders." (PMID 35573698, 2022). "Consistent with our findings, previous studies have shown that LncRNA RPPH1 promotes colorectal cancer metastasis by interacting with TUBB3 and promoting exosome-mediated macrophage M2 polarization." (PMID 38459596, 2024). "For example, RPPH1 promotes colorectal cancer cell metastasis by binding to β-III tubulin (TUBB3) and enhancing M2 macrophage polarization." (PMID 36619232, 2023). "TUBB3 (Tubulin Beta 3 Class III), a main cytoskeletal microtubule protein engaged in various processes including cancer invasion and migration, is targeted by miR-200b in colorectal cancer leading to the suppression of migration and invasion of cancer cells." (PMID 36158660, 2022). "Since cancer cell-derived exosomes contain RPPH1, this lncRNA is able to affect TUBB3 expression in other surrounding cancer cells, encouraging colorectal cancer progression." (PMID 35055115, 2022). "The same effect, but in a different mechanism, was reported with miR-200b-3p in colorectal cancer, where, via targeting TUBB3, it reduced resistance to oxaliplatin and promoted apoptosis and growth inhibition in resistant cancer cells." (PMID 36158660, 2022). "LncRNA RPPH1 was identified to combine with TUBB3 and inhibit its ubiquitination, thus promoting colorectal cancer cells metastasis." (PMID 35541917, 2022). "In both male and female colorectal cancer cell lines, stable silencing of androgen receptors (AR) yielded significant downregulation of TUBB3/βIII-tubulin, raising the possibility that ARs play a significant role in driving TUBB3 expression." (PMID 35573698, 2022). "Furthermore, it was proven that RPPH1 physically binds to and stabilizes TUBB3 proteins in colorectal cancer cells." (PMID 35055115, 2022). "Additionally, recent studies have suggested that TUBB3 upregulates Snail and represses ECAD, and ubiquitination of TUBB3 is blocked by the long noncoding RNA RPPH1 during metastasis of colorectal cancer cells." (PMID 33256003, 2020). "The evidence supporting the predictive role of gene/protein expression of TYMS–5FU/Capecitabine in colorectal cancers, TUBB3-taxanes in NSCLC and MGMT–temozolomide in brain tumors was modest and mainly from level III observational studies and level IV pre-clinical studies." (PMID 27888622, 2017). "Importantly, in male colorectal cancer cells, the AR-dependent TUBB3 regulatory pathway is constitutively activated via testicular androgen, while in colorectal cancer cell lines derived from women TUBB3 is only inducible upon serum starvation." (PMID 35573698, 2022). "To test whether TUBB3 overexpression is induced in other cell lines selected for taxol-resistance, we generated taxol-resistant cell lines derived from a colorectal carcinoma (HCT116), an osteosarcoma (U2OS), and two triple-negative breast cancer cell lines (Cal-51 and HCC1806)." (PMID 29069726, 2017). "Mechanistically, RPPH1 binds to TUBB3 to prevent its ubiquitination and then induces EMT in colorectal cancer cells." (PMID 36619232, 2023).
lung cancer (13 papers, 2011 to 2025). A malignant neoplasm involving the lung. "Studies in lung cancer have shown that high expression levels of brain-specific TUBB3 are associated with vincristine resistance in a preclinical setting, which has been further confirmed in patients with advanced NSCLC." (PMID 25705237, 2015). "The lung transcriptomic data of EMR mice show changes in the expression of genes previously identified in lung cancer cells, including metastasis associated in lung denocarcinoma transcript 1 (Malat1), synaptotagmin 7 (Syt7), and tubulin beta 3 class III (Tubb3)." (PMID 35619714, 2022). "Encouragingly, we also found this TUBB3+CD68 TAM subset in a 10× scRNA-seq dataset of human non–small cell lung cancer (NSCLC) biopsy with strong expression of neuronal genes including BMP7, SHANK, CHL1, and PAX6." (PMID 36206343, 2022). "In lung cancer, TUBB3 promotes tumorigenesis, EMT, and anoikis resistance through the PI3K/AKT pathway." (PMID 34234236, 2021). "Recent studies showed that LY294002 suppressed the expression of TUBB3 in colon cancer and lung cancer." (PMID 31412591, 2019). "Furthermore, we found increased mRNA of PIK3CB, PIK3CD, PIK3CG, BCL2, TUBB3 in ALK-positive lung cancer, which suggested activation of PI3K/AKT signaling pathway." (PMID 34234236, 2021). "The report shows TUBB3 is expressed in high levels in lung cancer cell lines, and by using RNAi technology, it was found that TUBB3 mediates sensitivity to paclitaxel in NSCLC cells, and high levels of TUBB3 expression are associated with paclitaxel and docetaxel resistance in vitro." (PMID 22439756, 2012). "Additionally, SLUG has been shown to directly interact with SOX9 to promote the formation of cancer stem-like cells in lung cancer, and there is the recent speculation that TUBB3 may be playing a role in the maintenance of cancer stem like cells." (PMID 35573698, 2022). "However, the fact that TUBB3 is so highly expressed in SCLC may be one reason why the disease tends to behave more aggressively than other types of lung cancer." (PMID 24396456, 2014).